LLGL2 (LLGL scribble cell polarity complex component 2)
Description:
Part of a complex with GPSM2/LGN, PRKCI/aPKC and PARD6B/Par-6, which may ensure the correct organization and orientation of bipolar spindles for normal cell division. This complex plays roles in the initial phase of the establishment of epithelial cell polarity.
Synonyms: HGL; Hugl-2; LGL2
Tractability: Antibody: its Gene Ontology location is reachable by antibodies, with medium confidence. PROTAC: ubiquitination databases record sites on it.
Gene: Protein-coding gene on chromosome 17 (75,525,080 to 75,575,215, forward strand). Ensembl gene ENSG00000073350.
Subcellular location: Cytoplasm
Subcellular location (Human Protein Atlas): Cytosol; Vesicles
Gene Ontology:
Molecular function: PDZ domain binding; protein binding; GTPase activator activity; myosin II binding
Biological process: L-leucine transport; regulation of establishment or maintenance of cell polarity; cortical actin cytoskeleton organization; establishment of spindle orientation; establishment or maintenance of epithelial cell apical/basal polarity; Golgi to plasma membrane transport; regulation of Notch signaling pathway
Cellular component: cytoplasm; cytosol; adherens junction; cortical actin cytoskeleton; plasma membrane
Genetic constraint (gnomAD): Loss-of-function variants: 83 observed, 122.08 expected, observed/expected ratio (o/e) 0.68, 90% interval 0.57 to 0.82. The upper end of that interval is the gene's LOEUF score, 0.82, which puts it in group 3 of 6, group 1 being the genes least tolerant of losing a copy. Missense variants: 1,273 observed, 1,412 expected, observed/expected ratio (o/e) 0.9, 90% interval 0.86 to 0.94. Synonymous variants: 577 observed, 588.28 expected, observed/expected ratio (o/e) 0.98, 90% interval 0.92 to 1.05.
Homologues: Orthologues: macaque LLGL2 (98% identical), chimpanzee LLGL2 (96% identical), dog LLGL2 (92% identical), pig LLGL2 (92% identical), mouse Llgl2 (91% identical), rat Llgl2 (90% identical), rabbit LLGL2 (90% identical), guinea pig LLGL2 (88% identical), tropical clawed frog llgl2 (72% identical), zebrafish llgl2 (66% identical), Drosophila melanogaster l(2)gl (36% identical), Caenorhabditis elegans lgl-1 (19% identical). Paralogues in human: LLGL1 (55% identical), STXBP5 (30% identical), STXBP5L (29% identical).